RNU4-72P (RNA, U4 small nuclear 72, pseudogene)
Gene: Small nuclear RNA gene on chromosome 6 (85,751,581 to 85,751,753, forward strand). Ensembl gene ENSG00000222686.
Homologues: Orthologues: chimpanzee U4 (98% identical), rat LOC120097288 (45% identical), dog U4 (42% identical), guinea pig U4 (42% identical). Paralogues in human: RNU4-36P (51% identical), RNU4-39P (48% identical), RNU4-43P (48% identical), RNU4-51P (47% identical), RNU4-49P (47% identical), RNU4-52P (47% identical), RNU4-59P (47% identical), RNU4-10P (46% identical), RNU4-70P (46% identical), RNU4-90P (46% identical), RNU4-24P (46% identical), RNU4-29P (46% identical), and 80 more.